MAVS (mitochondrial antiviral signaling protein)
Diseases named in the same sentence as MAVS in open-access papers (continued):
Sharing a sentence is not in itself a finding about the gene and the disease.
infection (continued). "Therefore, we asked whether the combined cellular and humoral responses observed in the MAVS-/- mice following the WNV-MAD infection were sufficient to protect them from a lethal WNV-TX infection." (PMID 31242236, 2019). "As MAVS works as a vital adaptor of mediating effective responses against a variety of DNA or RNA viruses, multiple strategies have been used to restrict host innate immune responses by regulation or modification of MAVS to facilitate its infection, including phosphorylation, ubiquitination." (PMID 30587113, 2018). "We previously demonstrated that WNV infection of mice deficient in mitochondrial antiviral-signaling protein (MAVS), the signaling adaptor for RNA helicases such as RIG-I, resulted in increased death and dysregulated immunity, which correlated with a failure of Treg expansion following infection." (PMID 28094802, 2017). "We hypothesized that Tregs may directly detect infection by WNV through the RLR signaling pathway with strict dependence on the MAVS adaptor protein for downstream signaling, thereby altering the suppressive capacity of Tregs and the ensuing anti-viral immune response." (PMID 28094802, 2017). "Furthermore, molecular studies revealed that following infection of cells with CVB3, c-FLIPL associates with mitochondrial antiviral signaling protein (MAVS), increases caspase-8 activity and type I IFN production, and reduces viral replication, whereas c-FLIPS promotes the opposite phenotype." (PMID 24816846, 2014). "Importantly, these data demonstrate that non-human primates are susceptible to infection by viruses that antagonize MAVS in a manner similar to HCV." (PMID 22427742, 2012). "No Noxa was detectable upon infection of MAVS-deficient MEFs." (PMID 21698224, 2011). "We note from co-immunoprecipitation experiments, that IKKγΔ associates with MAVS in the absence of ssRNA infection, suggesting to us, that IKKγ-MAVS complex may be a stable, pre-formed complex whose activity is initiated by binding activated RIG-I." (PMID 19956647, 2009). "Given the critical roles of TBK1 and IRF3 in RIG-I/MAVS-initiated IFN-inducing signaling pathway, we explored the role of SVCV-P-TBK1-IRF3 co-phase separated condensates during SVCV infection." (PMID 41363845, 2026). "cGAS KO only moderately reduced ISRE promoter activation by HIV-1 F191A Nef infection, while type I IFN signaling was almost completely abrogated upon MAVS KO." (PMID 41354661, 2025). "Modulation of IFN responses is also predicted to occur through NLRX1 negative regulation of MAVS/RIG-I and NF-κB following SeV infection, vesicular stomatitis virus (VSV), and encephalomyocarditis virus (EMCV) infection." (PMID 40356929, 2025). "The transcript and protein levels of IFN-α, IFN-β, RIG-I, MDA5, MAVS, TRAF3, TBK1, and IRF3 in the PRRSV-ICs-infected cell group were significantly diminished at 12 h and 24 h post-infection compared to those in the PRRSV-PNI-infected cell group." (PMID 41012704, 2025). "RNA virus (e.g., encephalomyocarditis virus EMCV) infection promotes RIG-I–MAVS interaction, thereby releasing MAVS from RNF115 to activate immune signaling." (PMID 40519923, 2025). "In summary, these results demonstrated that infection with a virulent CSFV Shimen strain can induce the expressions of TRAF1, RIG-I, MAVS, IRF1, and ISG15." (PMID 38995016, 2024). "This does not seem surprising since our previous work indicated that the level of Fis1 elevated at the late stages of infection with ECTV in L929 cells, providing the opportunity for close contact between MAVS and Fis1." (PMID 39338909, 2024). "Our current work indicated that colocalization of MAVS and Drp1 was elevated in the course of ECTV infection in L929 cells with normal and elongated mitochondrial networks." (PMID 39338909, 2024). "WT HEK293T cells induced higher levels of IFN-β mRNA than DDX11−/− and MAVS−/−HEK293T cells in response to SeV and VSV-GFP infection or poly(I:C) stimulation." (PMID 39470258, 2024).
infection (continued). "The mRNA expression levels of RIG-I, MDA5 and key adapter proteins, including MAVS, IRF7 and NF-κB, were significantly upregulated in the infection group at 24 hpi and 48 hpi." (PMID 39502173, 2024). "The ectopic overexpression of MAVS can induce IFN production and VHSV Ia infection inhibited fMAVS-induced IFN induction 24 hpi that was decreased at later times." (PMID 36851680, 2023). "During secondary infections with RSV, memory cell populations rapidly expand and induce a virus-specific immune response in a MAVS- and IFN-α-dependent manner." (PMID 37896776, 2023). "The RT-qPCR results showed that all the signaling adaptors decreased the expressions of PEDV N mRNA at various levels at 48 h and 72 h post-infection, with TRIF, MAVS, and STING being very significant in inhibition of PEDV at 72 h post-infection." (PMID 37631972, 2023). "Infection with the YT strain upregulated the expression level of OASL, recording a 300-fold increase, whereas the level of MAVS was downregulated compared to that in the normal liver." (PMID 37063902, 2023). "To better understand the degradation processes of MAVS and IRF3, we analyzed the endogenous levels of these proteins in HT-29 cells infected with rSA11 and rSA11/WaVP3 viruses over the course of infection." (PMID 37905816, 2023). "For example, NLRX1 negatively regulates infection-induced IFN-I signaling and IL-6 production in primary MEFs by inhibiting the interaction between MAVS and RIG-I." (PMID 37528226, 2023). "In fact, MAVS (or IPS-1) has been found to be upregulated in the kidney and brain of tilapia fish during late stages (96 hours post-infection) of TiLV infection." (PMID 37622112, 2023). "In the TRIF, MAVS, and STING siRNA-treated Vero cells, PEDV N mRNA and N protein expressions were obviously increased at 72 h post-infection relative to control siRNA-treated cells." (PMID 37631972, 2023). "A negative regulator of IFN pathways or positive regulator of MAVS, highly induced upon MARV or PRV3M infection." (PMID 37661999, 2023). "WT, MyD88 KO, and MAVS‐KO THP1 cells produced low levels of CXCL10 at baseline, and these were increased after infection with VZV (Fig EV1D)." (PMID 35670106, 2022). "After infection of cells with Sendai virus or treatment with poly (I:C), SERINC5 is recruited to mitochondria, where it is colocalized and interacts with mitochondrial antiviral signaling protein (MAVS), enhancing its polymerization." (PMID 35433679, 2022). "IFN-β signaling upon JUNV infection was also shown to be dependent on MAVS, as IFN-β levels were abrogated in Candid#1-infected MAVS-knockout cells, resulting in higher viral titers." (PMID 35746604, 2022). "Overall, these observations indicate distinct MAVS-dependent mechanisms regulating TRM cell expansion and TRM cell functionality during RSV secondary infection." (PMID 35108347, 2022). "EZH2 negatively regulates mitochondria-mediated antiviral innate immune responses by blocking the RIG-I/MAVS RNA recognition pathway, and inhibition of EZH2 activates infection-induced IFN-β expression." (PMID 33436557, 2021). "Considering that SARS-CoV-2 deploys Nsp5 to simultaneously inactivate RIG-I and MAVS, we reasoned that endogenous RIG-I and MAVS are functionally nullified by SARS-CoV-2 during infection." (PMID 34544279, 2021). "In the TRIF, MAVS and STING siRNA-treated Marc-145 cells, the PRRSV N protein expressions were substantially increased at 48 h and 72 h post infection relative to control siRNA-treated cells." (PMID 34696285, 2021). "We further performed endogenous co-immunoprecipitation experiments, which indicated that RNF90 interacted with MAVS in untreated PMA-THP1 cells, and VSV infection enhanced the interaction at 4 h after infection." (PMID 34512666, 2021).
infection (continued). "In addition, increased mitochondrial density (i.e., increased number and size of mitochondria) in all tissues affected by an increased metabolic rate because of exercise training may increase the density of MAVS, which enhances the anti-viral response following infection by SARS-CoV-2." (PMID 34564326, 2021). "Mitochondrial antiviral signaling protein (MAVS), an adaptor protein, is activated by RIG-I, which is critical for an effective innate immune response to infection by various RNA viruses." (PMID 34880843, 2021). "Upon infection with the Peste des Petits Ruminants Virus (PPRV, genus Morbillivirus), the level of MAVS was greatly reduced." (PMID 33807534, 2021). "The RT-qPCR results show that the all the signaling adaptors decreased the expressions of PRRSV N mRNA in varying degrees at 24 h, 48 h and 72 h post infection, with the TRIF and MAVS as the most effective inhibitors of PRRSV replication." (PMID 34696285, 2021). "The expression levels of zbTRIM25 and its downstream genes, RIG-I, MAVS, TRAF3, IRF3, and IFN 1 decreased to some different extent at 24 h post RGNNV infection in miR-202-5p mimics transfected ZBE3 cells." (PMID 32120903, 2020). "The MAVS triggers the type I IFN signaling by another viral RNA sensor, DDX3, which interacts with the abortive HIV-1 RNA upon infection." (PMID 33343516, 2020). "TRIM25 is known to stabilize RIG-I CARD domain interaction with MAVS CARD domains and increase IFN production during an infection." (PMID 32477965, 2020). "TBK1 k.o. cells have a ~10-fold lower IFN-β induction upon infection with EMCV-LZn, transfection of vRNA or upon overexpression of MAVS." (PMID 32667958, 2020). "The expression levels of RIG-I, MDA-5 and MAVS mRNA in PCV2-PIECs group were higher than those in the PIECs group at 12 and 24 h post-infection (hpi) (P < 0.05) while substantially increased at 24 hpi (P < 0.01)." (PMID 32727484, 2020). "Immunoblotting of the RIG-I/MAVS/NF-κB signaling pathway in HFDPCs showed that RIG-I protein was increased by DENV-2 at days 1, 2, and 33 post-infection." (PMID 32121148, 2020). "RIG-I and MDA5 activation by HCV occurs in a sequential and MAVS-dependent manner, as the IFN response is mediated by RIG-I at early stages of infection while the action of MDA5 takes place subsequently." (PMID 33613561, 2020). "Another miRNA (Mir-3470b) was upregulated after infection with bovine ephemeral fever virus (BEFV) and promoted viral replication by targeting MAVS to inhibit antiviral signal transduction." (PMID 32973718, 2020). "Intriguingly, MAVS-/- mice also had elevated levels of GC B cells compared to WT mice at 7- and 10-days post WNV-MAD infection." (PMID 31242236, 2019). "Since the discovery of the intracellular RNA sensing system, many immune evasion proteins that target RLRs or MAVS have been identified, mostly in viruses with an RNA genome, for which RIG‐I and/or MDA5 are the key PRRs during infection." (PMID 30499584, 2019). "Later in infection, when IFIT1 is highly expressed in the cytoplasm, IFIT1 prevents induction of type I IFN by interfering with MAVS signalling." (PMID 31372503, 2019). "Following infection with WNV-MAD, MAVS-/- mice developed significantly higher serum WNVE-specific IgM and IgG than WT mice." (PMID 31242236, 2019). "We observed changes in the distribution of MAVS and in overall mitochondrial morphology (using the TOM20 marker) upon infection of 3T3 cells with a West Nile virus (WNV) replicon." (PMID 30715798, 2019). "We noticed that some studies have shown that protein levels of MAVS, or TRAF3, or TRAF6 were downregulated to some extent after infection with different viruses." (PMID 29734366, 2018). "For instance, miR-22, miR-125a (or -b) and miR3570b have been indicated to participate in modulating the expression of MAVS upon Japanese encephalitis virus (JEV), influenza A virus (IAV) and rhabdovirus in teleost fish infections, respectively." (PMID 30587113, 2018).
infection (continued). "While RIG-I KO cells expressing NLS-RIG-I showed substantial IRF3 nuclear translocation upon PAfsΔNS1 infection, ablation of MAVS abolished NLS-RIG-I-mediated IRF3 activation in RIG-I-MAVS DKO cells." (PMID 30097581, 2018). "To further determine the importance and relative contribution of MAVS degradation to RV replication in vivo, we compared fecal RV antigen shedding induced by EW and RRV infection in WT and Mavs-/- pups over a 12 day course." (PMID 30460894, 2018). "In contrast to what we observed during lytic reactivation, individual depletion of RIG-I, MDA5, or MAVS, only slightly increased KSHV de novo infection." (PMID 30451863, 2018). "In sum our data show that 1) MAPL is required for the innate immune response, 2) that it interacts and SUMOylates RIG-I upon infection, and 3) that MAPL is required for the activation of RIG-I to bind MAVS and signal the transcriptional response." (PMID 28273895, 2017). "MAVS was found as a MAPL partner in uninfected cells, and this interaction was reduced during infection." (PMID 28273895, 2017). "Influenza virus can be recognized by RIG-I during infection and activates type-I interferon production by signaling transduction from RIG-I, MAVS, and TBK1/IKK-ξ complex to IRF3." (PMID 28392790, 2017). "We also found that IBV can cleave MAVS, an adaptor protein downstream of RIG-I and MDA5 that acts as a platform for antiviral innate immunity at an early stage of infection." (PMID 29132350, 2017). "Single-stranded or double-stranded viral RNAs accumulated inside cells after infection are recognized by RLRs and TLR3, which recruit the adaptor proteins mitochondrial antiviral signaling protein (MAVS) and TRIF, respectively." (PMID 26811330, 2016). "Taken together, these results indicate that IFN-β induction is mediated by RIG-I during IIV-6 infection and that MDA5, MAVS, and Dicer likely play a lesser role, in the activation of an IFN-β response during IIV-6 infection." (PMID 27824940, 2016). "The expression of MAVS, IRF-3/7, and type I interferons (IFN-α and IFN-β) are all altered post-infection." (PMID 26021751, 2015). "During infection with a RNA virus, the mitochondrial antiviral signaling protein (MAVS/VISA/Cardif/IPS-1) has been recently uncovered to seed a critical protein complex on the mitochondrial outer membrane." (PMID 24651600, 2014). "Here we show that airway epithelia, the primary target of influenza A virus, produce both IFN I and III upon infection, and that induction of both depends on the RIG-I/MAVS pathway." (PMID 24278020, 2013). "Over-expression of MAVS activates NF-κB and IRF3 and induces type I IFNs, resisting infection of Vesicular Stomatitis Virus (VSV) and Sendai Virus (SeV)." (PMID 23249700, 2012). "The cells were harvested 24 h after infection and whole cell lysates were western blotted for RIG-I, MAVS and NS1." (PMID 22383950, 2012). "In this study, pre- or post- infection with CVB3, exogenous MAVS was introduced into HeLa cells and the anti-CVB3 activity and mechanism of MAVS were investigated." (PMID 23249700, 2012). "MAVS was immunoprecipitated from the cell extracts at different times post-infection and the presence of PKR and RIG-I was examined in the immunocomplexes, as well as that of TRAF3, used as marker of activation of the MAVS signaling pathway." (PMID 22022264, 2011). "Infection of HeLa cells with both E7 and EV71 led to the significant reduction of MAVS and TRIF expression, which corresponded with the appearance of the newly replicated viral protein VP1." (PMID 21436888, 2011). "To estimate the time-frame required to study IFN induction before its abrogation upon the action of NS3/4A, we first established the kinetics of MAVS cleavage in the two HCV permissive cell lines Huh7.25/CD81 and Huh7.5 following HCV infection." (PMID 20485506, 2010).
infection (continued). "Altogether, our data indicate that HCV can activate the IFN induction pathway within 12 hrs after infection, but blocks it prior to the NS3/4A-mediated cleavage of MAVS." (PMID 20485506, 2010). "Here we report the use of HCV permissive Huh7.25.CD81 cells to analyse the effect of HCV on the RIG-I/MAVS-mediated IFN induction pathway during the early hours after infection, before the HCV NS3/4A protease can cleave MAVS and abrogate this pathway." (PMID 20485506, 2010). "For HSV, TLR2, TLR3, TLR9, the MAVS pathways and the RNA polymerase III pathway have been identified as sensing the infection and inducing the production of IFN-α/β and cytokines." (PMID 21994567, 2009). "Infection efficiency in each cell line was monitored by GFP positivity, which was similar between MAVS wildtype and knockout MEFs." (PMID 19404494, 2009). "In conclusion, this study preliminarily elucidates the mechanism by which cpBVDV/ncpBVDV infection-induced autophagy selectively degrades MAVS via BECN1–MAVS interaction, thereby suppressing the RIG-I–MAVS signaling pathway and impairing antiviral innate immunity." (PMID 41363843, 2026). "Moreover, AF-9 strain infection or poly (I: C) stimulation led to upregulation of the production of RIG-I, MDA5, MAVS, TRAF3, and TBK1 and phosphorylation of TBK1 and IRF3 in PAMs." (PMID 41012704, 2025). "The transcript and protein levels of IFN-α, IFN-β, RIG-I, MDA5, MAVS, and TRAF3 in the PRRSV-infected cell group and poly (I: C)-stimulated cell group were significantly elevated at 12 h and 24 h post-infection compared to those in the mock-infected cell group." (PMID 41012704, 2025). "We observed cleavage of MDA5, MAVS, and RIG-I from 6 hpi onwards during CVB3–2Awt infection." (PMID 40875754, 2025). "The transcript and protein levels of IFN-α, IFN-β, RIG-I, MDA5, MAVS, TRAF3, TBK1, and IRF3 in the PRRSV-infected cell group by anti-FcγRI IgG pre-treatment were significantly declined at 12 h and 24 h post-infection compared to those in the PRRSV-infected cell group by RNI pre-treatment." (PMID 41012704, 2025). "Infection of mouse fibroblast L929 cells with ectromelia virus (ECTV) revealed that the alteration of mitochondrial network morphology regulates MAVS-dependent innate immunity, and mitochondrial network fragmentation inhibits the MAVS-mediated immune response." (PMID 40076578, 2025). "It is also not known whether deficiency of MAVS signaling of long-lived CX3CR1+ CNS cells might affect the outcome of T-cell responses due to potential differences in the pool of presented epitopes that would drive cross-presentation from BAMs in our infection model." (PMID 40619428, 2025). "Compared to control NLRP1+ THP-1/PMA cells, knockdown of MAVS or STING in NLRP1+ THP-1/PMA macrophages did not impact infection efficiency." (PMID 40920844, 2025). "This phosphorylation is essential for robust induction of type I IFNs in response to infection with RNA viruses, but not for MAVS-mediated apoptotic signaling, suggesting a specific role for phosphorylation in tailoring antiviral innate immunity." (PMID 40837220, 2025). "Because MAVS was localized in mitochondria and interacts with DDX11, we further isolated the mitochondrial fraction and observed increased localization of DDX11 to mitochondria in HEK293T cells after infection with SeV." (PMID 39470258, 2024). "Levels of infection were equivalent between WT and STING- or MAVS-null cells." (PMID 38778414, 2024). "We therefore decided to use KO cell lines for the host factors MAVS and PKR to assess whether preventing the induction of these two antiviral signaling pathways during EMCV-LZn infection affects EV and EV-enclosed virus release." (PMID 38662794, 2024). "While MERS-CoV infection led to the cleavage of MAVS, MAVS was not cleaved upon infection with SARS-CoV-2, even though virus replication and release of viral progeny at 24 h post-infection was comparable to that of MERS-CoV." (PMID 38400032, 2024).